CD1A (CD1a molecule)
Diseases named in the same sentence as CD1A in open-access papers (continued):
Sharing a sentence is not in itself a finding about the gene and the disease.
Langerhans cell sarcoma (4 papers, 2013 to 2020). A neoplastic proliferation of Langerhans cells with overtly malignant cytologic features. "For example, negative S-100 staining can differentiate FDCS from interdigitating DC sarcoma, and negative staining for CD1a can distinguish FDCS from Langerhans cell sarcoma." (PMID 32871936, 2020).
laryngeal carcinoma (4 papers, 2021 to 2024). Carcinoma that arises from the laryngeal epithelium. "In a previous study conducted in our laboratory, CD1a-DCs were found to be associated with unfavorable clinical outcomes in patients with advanced laryngeal cancer who had undergone total laryngectomy as the initial treatment." (PMID 38396770, 2024). "Our previous research has indicated that the infiltration of CD1a-DCs into the primary lesion is associated with an unfavorable prognosis for patients with advanced laryngeal cancer who had undergone a total laryngectomy as their initial treatment." (PMID 38396770, 2024). "We have analyzed the association between the infiltration of CD1a+ DCs into cancer tissue and clinicopathological factors in patients with advanced laryngeal cancer." (PMID 34461859, 2021). "We investigated the infiltration of CD1a+ DCs and its association with clinicopathological factors in patients with advanced laryngeal cancer who underwent a total laryngectomy as an initial treatment." (PMID 34461859, 2021). "Our results demonstrated that the infiltration of CD1a+ DCs was associated with unfavorable clinical outcomes in patients with advanced laryngeal cancer who underwent a total laryngectomy as the initial treatment." (PMID 34461859, 2021). "The density of tumour residing CD1a+ DCs has also been reported in a variety of human cancers, and their number in colon, gastric, lung and laryngeal carcinomas was positively associated with improved outcome." (PMID 33919875, 2021). "We anticipate that further studies will validate our findings and ultimately elucidate the function(s) of tumor-infiltrating CD1a+ DCs in advanced laryngeal cancer." (PMID 34461859, 2021). "Tumor-infiltrating CD1a+ DCs have been reported to be associated with clinical outcomes in carcinomas of various organs, but the clinical impact of CD1a+ DCs in laryngeal cancer remains to be unequivocally established." (PMID 34461859, 2021). "We considered treatment naïve cases were more suitable for this study because there is a paucity of knowledge about the role(s) of CD1a+ DCs in laryngeal cancer." (PMID 34461859, 2021). "However, the roles of tumor-infiltrating CD1a+ DCs and their clinical impact on patients with laryngeal cancer remain to be elucidated." (PMID 34461859, 2021). "Only 1 of these 4 previous studies investigated CD1a+ DC infiltration in laryngeal cancer." (PMID 34461859, 2021). "Thus, the present study, we believe, is the first to report an association between poor surgical outcomes and tumor infiltrating CD1a+ DCs in laryngeal cancer." (PMID 34461859, 2021). "However, the role(s) of CD1a+ DCs in cancer tissue remain to be unequivocally established, as do the reasons why the invasion of CD1a+ DCs is correlated with a poor prognosis of patients with advanced laryngeal cancer." (PMID 34461859, 2021).
oral squamous cell carcinoma (4 papers, 2020 to 2024). "Accumulation of immature CD1a+ DCs in metastatic oral squamous cell carcinoma (OSCC) LNs was associated with both increase in regulatory T cells and a drop of cytotoxic cell numbers, supporting the hypothesis of the immunosuppressive microenvironment that in turn contributes to cancer spread." (PMID 35955602, 2022). "Immunohistochemical staining for CD4, CD8, FoxP3, CD1a, and p16 was performed in 131 oral squamous cell carcinomas from smokers/drinkers and never-smokers/never-drinkers." (PMID 37345025, 2023).
ovarian carcinoma (4 papers, 2003 to 2019). A malignant neoplasm originating from the surface ovarian epithelium. "Moreover, CD45RO + T lymphocytes and dendritic cells CD1a + or S-100 + is associated with a higher survival rate in patients with epithelial ovarian cancer." (PMID 30917846, 2019). "The results obtained show that ovarian cancer type II lysates induce differentiation of monocytes into macrophage-like cells with a CD1a+/HLA-DR+/CD83− phenotype and significantly higher CD86/HLA-DR expression." (PMID 28589429, 2017). "The density of CD1a-positive DC has been directly related to survival for tongue carcinomas and reduced tumour recurrence in ovarian carcinoma." (PMID 12888826, 2003).
sarcoidosis (4 papers, 2013 to 2022). Sarcoidosis is a multisystemic disorder of unknown cause characterized by the formation of immune granulomas in involved organs. "A comparison of BAL samples of patients with PLCH, sarcoidosis or IPF, found that patients suffering from PLCH had a significantly higher number of CD1a+ and langerin+ cells than the subjects with sarcoidosis and IPF." (PMID 36160158, 2022). "Numbers of DCs in BAL of IPF patients are similar to controls but more immature.Fewer CD1a+ DCs (most likely cDC2) in BAL of sarcoidosis patients." (PMID 28507549, 2017). "There are a few reports demonstrating the expression of CD1a on mDCs in the local inflammatory sites in sarcoidosis." (PMID 23497225, 2013). "CD1a+mDC count was equivalent in the sarcoidosis group: 238.5 (139.8, 362.8) and healthy controls: 351.0 (217.0, 462.0), but was significantly decreased in the atopy group: 215.0 (118.0, 279.0) (P < 0.05)." (PMID 23497225, 2013). "CD1a-mDC count in the atopy group: 205.0 (93.0, 324.5) was greater than in both controls: 92.5 (53.5, 144.5) (P < 0.05) and the sarcoidosis group: 79.0 (44.5, 135.0) (P < 0.05)." (PMID 23497225, 2013). "Sarcoidosis patients showed decreased peripheral total and myeloid DC count with similar population of both CD1a+ mDC and CD141+mDC subsets compared to the control subjects." (PMID 23497225, 2013). "An investigation in the BALF of inflammatory diseases showed an increase of CD1a-mDCs in sarcoidosis." (PMID 23497225, 2013). "We expected a predominance of CD1a+mDC count in peripheral blood in patients with sarcoidosis." (PMID 23497225, 2013). "In this study, we have reported differences of peripheral blood DC subsets between sarcoidosis and atopic diseases using four-color flow cytometry, and have analyzed the adequacy of CD1a and CD141 as a marker for mDC1 and mDC2, respectively by the production of IL-12p40." (PMID 23497225, 2013). "Contrary to our expectation, no such differences in numbers of CD1a+mDCs and CD1a-mDCs were seen between sarcoidosis and controls." (PMID 23497225, 2013). "We therefore conducted a study to analyze peripheral blood DC subsets, including mDC1 and mDC2, using CD11c, CD123, CD1a and CD141, in patients with sarcoidosis as a Th1-mediated disease and atopic diseases as Th2-mediated diseases compared to healthy controls." (PMID 23497225, 2013).
tuberculosis (4 papers, 2012 to 2021). A chronic, recurrent infection caused by the bacterium Mycobacterium tuberculosis. "The study found CD1a-DDM tetramer+ T cells in the peripheral blood of tuberculosis patients and showed that DDM is capable of binding to a recombinant TCR following incubation with CD1a." (PMID 34956202, 2021). "Human group 1 CD1 molecules (CD1a, CD1b, and CD1c) bind a pool of lipid antigens expressed by mycobacteria and present them to specific T cells, thereby mediating an effective pathway for host defense against tuberculosis." (PMID 22536277, 2012).
ulcerative colitis (4 papers, 2016 to 2023). An inflammatory bowel disease involving the mucosal surface of the large intestine and rectum. "This study suggested that monocytes expressing CD1a may be sensors and mediators of ulcerative colitis inflammation, and that CD1a could be a potential therapeutic target for the disease." (PMID 34412691, 2021).
Autoimmunity (3 papers, 2017 to 2021). The occurrence of an immune reaction against the organism's own cells or tissues. "In conclusion, based on our findings we suggest that 5-HT2B represents an important brake mechanism intrinsic to inflammatory antigen-presenting cell (APC) subsets, such as CD1a+ moDCs, that prevent excess inflammation, autoimmunity and consequent tissue destruction." (PMID 29379077, 2018). "Lipids released by PLA2 and presented by CD1a expressing monocytes and macrophages might induce autoimmunity by activation Th1 (our own results) or Th22 cells." (PMID 29282132, 2017). "T cells that recognize CD1a may be implicated in the pathology of many disease states including cancer and autoimmunity but have not been studied in the context of LCH despite the expression of CD1a by LCH cells." (PMID 34956202, 2021).
Barrett's metaplasia (3 papers, 2005 to 2022). "We also recently described that CD1a could be expressed in metaplastic epithelium of Barrett's oesophagus, both gastric and intestinal types, while normal gastric and colonic mucosa were negative to this marker." (PMID 15756258, 2005). "Moreover, the lack of CD1a expression in the dendritic cells of Barrett's metaplasia may predict its evolution toward oesophageal adenocarcinoma." (PMID 32377167, 2020). "The aim of the present work was to investigate the expression of CD1a in a series of Barrett's metaplasia (BM), gastric type (GTBM), with and without follow-up, in order to analyse whether its expression may help to diagnose this disease and to address the outcome." (PMID 15756258, 2005).
Barrett’s esophagus (3 papers, 2020 to 2022). Esophageal lesion lined with columnar metaplastic epithelium which is flat or villiform. "Moreover, the lack of CD1a expression in the dendritic cells of Barrett’s mataplasia may predict its evolution toward esophageal adenocarcinoma." (PMID 32565898, 2020).
cervical cancer (3 papers, 2021 to 2024). A primary or metastatic malignant neoplasm involving the cervix. "Other studies have found that the number of CD1a+DCs was significantly downregulated in some invasive cervical cancers." (PMID 36313765, 2022).
colorectal cancer (3 papers, 2007 to 2025). A primary or metastatic malignant neoplasm that affects the colon or rectum. "Particularly, expression of CD1a has been used to classify tumor DCs, for example, in breast and colorectal cancer." (PMID 29988364, 2018). "The prognostic role of dendritic cells (DCs) in colorectal cancer (CRC) and paired liver metastases (LM) remains unclear, particularly regarding the dynamics of immature CD1a+ and mature CD208+ subsets across anatomical compartments and synchronous versus metachronous disease." (PMID 41410751, 2025).
COVID-19 (3 papers, 2021 to 2024). A disease caused by infection with severe acute respiratory syndrome coronavirus 2. "On the other hand, the correlation of microRNA 16 and microRNA 21 expression with CD1a and CD11b was dramatically changed by 8-fold, 11-fold, and 7-fold, respectively, in COVID-19-positive AML patients." (PMID 38902412, 2024). "Here, for the first time, we identified that the changes in the association between some of the microRNAs and CD1a, CD2, and CD11b were the most apparent alterations among AML patients after infection with COVID-19." (PMID 38902412, 2024). "Moreover, the link between microRNA155, microRNA192, and CD1a was remarkably disturbed by ninefold in COVID-19-positive AML patients." (PMID 38902412, 2024). "We also noticed a remarkable change towards a negative correlation of microRNA137 expression with CD1a, CD11c and CD79a in COVID-19-positive AML patients." (PMID 38902412, 2024).
endometriosis (3 papers, 2013 to 2022). The growth of functional endometrial tissue in anatomic sites outside the uterine body. "The data presented herein support that endometrial CD91+ macrophages and CD1a+ dendritic cells of women with endometriosis display a decreased phagocytic capacity compared to controls." (PMID 35421980, 2022). "Notably, we found that endometrial CD91+ macrophages and CD1a+ dendritic cells overexpress SIRPα—which acts to inhibit efferocytosis by these cells—in women with endometriosis compared to controls." (PMID 35421980, 2022). "Interestingly, the anti-phagocytosis marker SIRPα (CD172a) was increased on phagocytic CD91+ macrophages and CD1a+ dendritic cells in cases versus controls in the proliferative phase, suggesting decreased phagocytic capacity of these populations in endometriosis patients." (PMID 35421980, 2022). "Notably, we found that endometrial CD1a+ dendritic cells also overexpress SIRPa in women with versus those without endometriosis, indicating that other endometrial phagocytic cells may also be dysregulated in women with endometriosis." (PMID 35421980, 2022). "The density of CD1a+ (immature) DCs is increased during the proliferative phase in the basal layer of the endometrium, and the density of CD83+ (mature) DCs is decreased across all stages of the menstrual cycle in women with endometriosis." (PMID 33807420, 2021).
gastric cancer (3 papers, 2020 to 2024). A primary or metastatic malignant neoplasm involving the stomach. "Several reports on many neoplasms, including thyroid and gastric cancer, proved that the infiltration of immature CD1a+ cells was associated with favorable clinical outcomes." (PMID 36768258, 2023). "Dendritic cells expressing Langerin, CD1a, S100, CD83, CD86, and BDCA-2 were detected in gastric cancer tissue by immunohistochemical analysis." (PMID 33198173, 2020).
juvenile xanthogranuloma (3 papers, 2017 to 2025). A benign histiocytic tumor that occurs during childhood; it is distinct from Langerhans cell histiocytosis. "Juvenile xanthogranuloma (JXG) is a rare non-Langerhans cell (LCH) histiocytic disorder with histologic features characteristic of dermal dendrocytes (fascin+, CD1a−, CD207−) and macrophages (CD14+, CD68+, CD163+, and factor XIIIa+)." (PMID 28512266, 2017).
leishmaniasis (3 papers, 2021 to 2024). Infectious disease that is transmitted through the bite of hematophagous female phlebotomine sand flies. "An unusual phenomenon of Leishmania amastigotes expressing the CD1a molecule and the possibility of using it as an immunodiagnostic tool was reported for the first time in 2012, during an immunohistochemical (IHC) expression study on leishmaniasis caused by L. major and L. tropica." (PMID 39523649, 2024). "Additionally, we emphasize the importance of replicating this experiment in studies investigating all clinical forms of leishmaniasis caused by L. donovani, including VL and PKDL, to evaluate the significance of CD1a clone MTB1 as a diagnostic marker of disease caused by this species." (PMID 39523649, 2024). "The current study showed that CD1a epidermal, dermal DCs, and CD68 macrophages are the most important cells that regulate the outcome of leishmaniasis." (PMID 33507940, 2021).
lymph node metastasis (3 papers, 2020 to 2024). "In EBV-negative cases, the high density of DCs expressing CD1a was correlated with advanced (pT2–4) T stage, venous invasion, lymphatic invasion, and lymph node metastasis (p < 0.05)." (PMID 33198173, 2020). "No high-density CD1a-DCs infiltration was observed in LNs without lymph node metastasis." (PMID 39684473, 2024).
periampullary adenocarcinoma (3 papers, 2016 to 2021). An adenocarcinoma that arises from the periampullary region. "Immune cell-specific expression of CD56, CD3, CD68 and CD1a was analysed by immunohistochemistry on tissue microarrays with tumours from 175 consecutive cases of periampullary adenocarcinoma, 110 of pancreatobiliary type (PB-type) and 65 of intestinal type (I-type) morphology." (PMID 27275582, 2016). "This study is, to our best knowledge, the first to investigate the prognostic role of tumour-infiltrating CD1a+, CD68+ and CD163+ and MARCO+ immune cells in periampullary adenocarcinoma, with particular reference to morphological type." (PMID 28673320, 2017).
periodontitis (3 papers, 2009 to 2025). An acute or chronic inflammatory process that affects the tissues that surround and support the teeth. "Además, cuando la encía se encuentra inflamada, la acumulación de placa bacteriana favorece el aumento de células CD1a+, y se encuentra una posible relación entre la periodontitis y la infección por VIH." (PMID 40612418, 2025).
rheumatoid arthritis (3 papers, 2014 to 2019). A chronic, systemic autoimmune disorder characterized by inflammation in the synovial membranes and articular surfaces. "Against this hypothesis is the observation, to the best of our knowledge, that similar inflammatory conditions such as familial hemophagocytic lymphohistiocytosis, rheumatoid arthritis and inflammatory bowel disease are not characterized by a predominance of CD1a+ cells." (PMID 25343480, 2014).
Sepsis (3 papers, 2012 to 2017). Sepsis is defined as life-threatening organ dysfunction caused by a dysregulated host response to infection. "IL-4&GM-CSF-differentiated MO obtained from mice surviving sepsis had significantly lower expression of CD1a and CD83, two exclusive markers for monocyte-derived immature and mature cells, respectively." (PMID 28507543, 2017). "Still, T cell-induced cytokine profiles were similar when sepsis and control CD1a+ DC were used, with comparable production of IL-10 and IFN-γ." (PMID 23071758, 2012). "We found profound decrease of MO→iDC in the humanized mice 28 days after sepsis, demonstrated by depressed expression of CD1a, CD83, and CD209, diminished production of IL-12p70, and depressed ability to stimulate T cells in mice after CLP as compared to SHAM or CONTR." (PMID 28507543, 2017). "However, CD1a+ DC derived from sepsis and controls differed strongly with respect to Foxp3 induction in proliferating T cells with a two- to three-fold stronger Foxp3 expression in CD25+ T cells activated by patients DC." (PMID 23071758, 2012).
thymic carcinoma (3 papers, 2007 to 2022). Thymic carcinoma (TC) is a type of thymic epithelial neoplasm characterized by a high malignant potential. "Immunohistochemical staining for PAX8, CD5, c-KIT, TdT, and CD1a also demonstrated features that are characteristic to thymic carcinoma." (PMID 34328560, 2021). "However, immunohistochemical evaluation, including expression patterns of PAX8, CD5, c-KIT, TdT, and CD1a that are characteristic to thymic carcinoma, confirmed the diagnosis in our patient." (PMID 34328560, 2021). "Helpful cytologic and immunocytochemical features in making the diagnosis of thymic carcinoma are clear-cut cytological atypia, absence of immature lymphocytes (CD1a+, CD99+), and expression of CD5 and CD70 by neoplastic epithelial cells." (PMID 17498299, 2007).
thymoma (3 papers, 2007 to 2022). A neoplasm arising from the epithelial cells of the thymus. "Recently, WHO had suggested a dozen of histochemical markers to differentiate type A and type B thymoma, including TdT, CD1a, CD99, PSMB11 (Beta5T), PRSS16, Cathepsin V, and desmin." (PMID 31967407, 2020). "Overall, the three specific proteins markers of immature T lymphocytes, namely TdT, CD1a, and CD99, were found at significantly higher level in type B thymoma than in type A (P < 0.05)." (PMID 31967407, 2020). "Small stromal lymphoid aggregates containing mature T lymphocytes (CD3+, CD5+, CD1a-, CD99-, Ki67 proliferation index <10%) and CD20+ B lymphocytes were observed in all B2 and B3 thymomas." (PMID 17498299, 2007). "On the other hand, beta-5t, CD1a, CK19, and TdT showed higher expression in thymomas." (PMID 35565429, 2022). "Type B2 and B3 thymomas showed a similar immunophenotype with a variable CK7 expression, and immature intratumoral non-neoplastic T lymphocytes (CD3+, CD5+, CD1a+, CD99+; Ki67 proliferation index >80%)." (PMID 17498299, 2007). "Similar to thymomas, mediastinal neuroendocrine neoplasms express CD57 and other neuroendocrine markers but are consistently negative for non-neoplastic immature lymphocytes (CD1a+, CD99+)." (PMID 17498299, 2007).